SCN2A (sodium voltage-gated channel alpha subunit 2)
Diseases named in the same sentence as SCN2A in open-access papers (continued):
Sharing a sentence is not in itself a finding about the gene and the disease.
epilepsy (continued). "MCD was detected in patients with SCN2A-related epilepsy (2/17, 11.8%) and SCN1A-related epilepsy (1/114, 0.9%)." (PMID 41573391, 2025). "Increases in genetic testing have prompted numerous reports identifying four VGSC genes of significant clinical importance in epilepsy: SCN1A, SCN2A, SCN3A, and SCN8A." (PMID 41007641, 2025). "In this single-center cohort of 139 pediatric patients with genetically confirmed SCN1A-, SCN2A-, SCN3A-, and SCN8A-related epilepsies, structural brain MRI abnormalities were identified in 37.4% of the patients." (PMID 41573391, 2025). "To address this gap, we analyzed structural brain MRI findings in a large single-center pediatric cohort with genetically confirmed SCN1A-, SCN2A-, SCN3A-, and SCN8A-related epilepsy." (PMID 41573391, 2025). "This study is one of the largest single-center comparative neuroimaging analyses of SCN1A-, SCN2A-, SCN3A-, and SCN8A-related epilepsies." (PMID 41573391, 2025). "Of these, 114, 17, 1, and 7 patients had SCN1A-, SCN2A-, SCN3A-, and SCN8A-related epilepsy, respectively." (PMID 41573391, 2025). "Contrary to earlier assumptions, structural MRI abnormalities are common in SCN-related epilepsies, particularly in SCN2A-and SCN8A-related epilepsies." (PMID 41573391, 2025). "Mutations in four evolutionary and functionally similar α subunit genes, SCN1A, SCN2A, SCN3A, and SCN8A, lead to neurological diseases, including various types of epilepsy." (PMID 41007641, 2025). "Abnormalities were most frequent in the SCN2A (70.6%) group, followed by the SCN8A (42.9%) and SCN1A (31.6%) groups; one patient with SCN3A-related epilepsy also exhibited abnormal findings." (PMID 41573391, 2025). "Many genetic polymorphisms play a role in the pathogenesis and treatment of epilepsy, e.g., SCN1A ABCG2, SCN1A, CYP3A5, and SCN2A." (PMID 39920787, 2025). "Abnormal MRI findings have also been reported in SCN2A, SCN3A, and SCN8A-related epilepsies, although most studies to date have been limited to case reports or small series, and imaging patterns remain poorly defined across genotypes." (PMID 41573391, 2025). "Variability in seizure phenotypes among SCN1A-mutated patients suggests potential interactions with other ion channel genes, such as SCN2A and SCN8A, underscoring the polygenic complexity of SCN1A-related epilepsies." (PMID 39906551, 2024). "Although these three genes show mutations in a wide spectrum of neurological diseases such as epilepsy, autism spectrum disorder (ASD), and intellectual disability, two of those, SCN1A and SCN2A, are major ones." (PMID 37219072, 2023). "Patients with SCN2A-related DEE and early infantile epilepsy respond well to sodium channel blockers, particularly phenytoin and carbamazepine." (PMID 38003469, 2023). "Eighty-one epilepsy-related genes were detected; the gene most frequently detected was KCNQ2 (nine times), followed by PRRT2 (seven times), SCN1A (six times), SCN2A (five times), SPTAN1 (four times), and TSC2 (four times)." (PMID 35571021, 2022). "Successful use of ASOs for severe epilepsies has been reported in preclinical models of SCN1A, SCN2A, and SCN8A encephalopathy." (PMID 36173683, 2022). "For example, protein truncating variants in SCN1A are more likely than missense variants to cause Dravet syndrome rather than milder epilepsies, and the electrophysiological consequences of particular SCN2A variants might predict age of onset and treatment response." (PMID 34031551, 2021). "Although hyperexcitability in Scn1a epilepsy mouse models has been largely associated with impaired firing in inhibitory neurons, several studies suggest that excitatory neuronal firing could also be altered as seen in a human iPSC SCN1A model and an SCN2A mouse model." (PMID 33658306, 2021).
epilepsy (continued). "Standardized terminologies, such as the terminology for seizures and epilepsies by the International League Against Epilepsy (ILAE), have changed since the initial description of SCN2A as a disease gene in 20011,18." (PMID 33731876, 2021). "In our study, we found the relationship between the SNPs screened from SCN1A, SCN2A and UGT2B7, respectively, and VPA responses in Chinese Han people with epilepsy." (PMID 32185219, 2020). "Mosaicism in the proband has been reported in other genes such as PCDH19 (8.3%, 6/73), SCN1A (1.3%, 4/320), SCN2A (6.4%, 7/110), and CDKL5 (8.8%, 8/91), according to a recent large‐scale study of epilepsy‐related neurodevelopmental disorders." (PMID 30891744, 2019). "Absence or absence-like epilepsies in patients with ASD and intellectual disability is consistent with absence-like seizures in mice with Scn2a-haploinsufficiencies." (PMID 30175250, 2018). "We find current evidence for this preferential enrichment among six epilepsy genes: CDKL5 (P = 1.1 × 10−12), KCNQ2 (P = 1.1 × 10−23), PCDH19 (P = 0.003), SCN1A (P = 9.7 × 10−9), SCN2A (P = 1.9 × 10−4), and SCN8A (P = 3.5 × 10−4)." (PMID 28864458, 2017). "However, not all patients with SCN2A mutations have been reported to have epilepsy." (PMID 24650168, 2014). "SCN2A, SCN3A, and SCN3B were upregulated in neurons, described to be involved in neuronal excitation and epilepsy pathogenesis." (PMID 23690787, 2013). "Identifying patients with epilepsy who would derive the greatest benefit from VPA therapy may involve the consideration of SCN1A rs3812718 and SCN2A rs2304016 genotypes." (PMID 38837984, 2024). "This study underscores the influence of SCN2A rs17183814 on VPA treatment efficacy.Effective antiepileptic treatment necessitates the maintenance of adequate drug concentrations, emphasizing the importance of therapeutic drug monitoring in epilepsy therapy." (PMID 38837984, 2024). "Although sodium channel blockers exhibit some efficacy in early-onset SCN2A-related epilepsy, OXC is not effective in all cases, and LCS and other sodium channel blockers can be used when OXC shows a poor response." (PMID 38174099, 2023). "Though GS967 has been shown to be an efficacious antiepileptic in rodent models of SCN1A, SCN2A, and SCN8A epilepsies, the safety, tolerability, and antiepileptic efficacy of GS967/Prax330 in human patients with refractory epilepsy remains to be fully investigated." (PMID 32244818, 2020). "More recently, de novo SCN2A mutations have also been identified in patients with intellectual disability (ID), autism spectrum disorder (ASD) or schizophrenia without overt epilepsy, enlarging thus the spectrum of SCN2A-associated disorders." (PMID 31501495, 2019). "Neuronal sodium channel genes, SCN1A, SCN2A and SCN8A, have been extensively involved in the pathophysiology of a broad spectrum of neurological disorders, including developmental and epileptic encephalopathy (DEE) in which epilepsy and neurodevelopmental comorbidities coexist." (PMID 41515912, 2025). "Cacna1g could be a potential therapeutic target for the treatment of Scn2a-related epilepsies that do not respond to sodium or potassium channel blockers." (PMID 39606727, 2024). "Notably, we did not identify variants within SCN2A and SCN8A genes, two genes previously associated with epilepsy and SUDEP." (PMID 32449611, 2020). "However, targeted gene panel sequencing for SCN1A, SCN2A, and GABRG2, which are associated with GEFS+, showed no pathogenic mutations in the 11 children subsequently diagnosed with epilepsy in this study." (PMID 33212914, 2020).
epilepsy (continued). "However, the SCN2A expression changes in epilepsy have not been discussed, particularly with reference to the cerebral cortexes of patients with primary or secondary temporal lobe epilepsy and normal brain cortex tissues." (PMID 24220630, 2014). "SCN9A is unlike the epilepsy-related VGSC-α subunit molecules SCN1A, SCN2A, SCN3A and SCN8A each of which is expressed primarily in brain, whereas SCN9A is expressed primarily in peripheral nerves." (PMID 33216760, 2020). "One of these genes is SCN2A, where initial large studies revealed a NDD phenotype but where more recent studies have reported patients with schizophrenia, with or without the other SCN2A-typical features, such as epilepsy and neurodevelopmental delay." (PMID 37662110, 2023).
autism (50 papers, 2012 to 2026). Persistent deficits in social interaction and communication and interaction as well as a markedly restricted repertoire of activity and interest as well as repetitive patterns of behavior. "For example, SCN1A-associated Dravet syndrome variants exhibited 3D positional correlations with SCN2A variants associated with autism (R = 0.31, P = 4.7e − 35), and Brugada syndrome variants in SCN5A (R = 0.29, P = 6.1e − 40)." (PMID 40624578, 2025). "SCN2A encodes the Nav1.2 voltage-gated sodium channel and is significantly reduced in individuals with autism." (PMID 40498018, 2025). "One notable gene, SCN2A, which encodes Nav1.2, the type II α subunit of the voltage-gated sodium channel, is among the strongest single gene candidates for autism susceptibility." (PMID 40053578, 2025). "Many genes are associated with autism spectrum disorders, and copy number variations and rare gene mutations (e.g., SHANK3, NRXN1, CHD8, SCN2A) are closely linked to autism." (PMID 39734494, 2024). "Our study establishes a key role of microglia in multi-species autism-associated models of SCN2A deficiency from mouse to human cells." (PMID 37841865, 2023). "A small subset of autism cases are monogenic in origin and can be directly tied to a single causal mutation, such as loss-of-function mutations in SCN2A which cause SCN2A syndromes." (PMID 32264956, 2020). "For example, one of the most significant candidate genes in the shared group, SCN2A, is an important autism-associated gene that is linked to voltage-gated sodium channel activity and ion channel activity." (PMID 32066658, 2020). "Loss-of-function mutations in the SCN2A gene, which encodes the voltage-gated sodium channel NaV1.2, are associated with autism rates up to 50%." (PMID 32264956, 2020). "Mutations of the SCN2A gene have also been reported in patients with autism as well as with benign familial infantile seizures, intractable epilepsy, infantile spasms and severe myoclonic epilepsy of infancy." (PMID 30071822, 2018). "For the known autism risk genes confirmed in previous studies, SCN2A is still the most frequently mutated in this study." (PMID 30564305, 2018). "Most notably, patient M01813 carried LGD DNMs in autism risk genes SCN2A and CDKL5, albeit the latter occurs near the terminal portion of the protein." (PMID 30564305, 2018). "The only child with a truncating mutation in SCN2A (case 48) presented with autism and clusters of seizures from 9 months of age." (PMID 26993267, 2016). "Previous findings of multiple de novo loss-of-function mutations in this gene family, particularly SCN2A, in autism and intellectual disability provide biological and genetic plausibility for this finding." (PMID 26196440, 2015). "In the literature, a gene SCN2A was reported as associated with autism, and two probands each carried a nonsense de novo mutation in this gene." (PMID 24651380, 2014). "For example, SCN2A (MIM: 182390) has been validated to be causative for autism (MIM: 209850) and early infantile epileptic encephalopathy-11 (EIEE11, MIM: 613721) but benign familial neonatal-infantile seizures-3 (BFIS3, MIM: 607745)." (PMID 24651380, 2014). "Gene mutations such as SCN2A mutations are found in patients with ID and autism." (PMID 36819340, 2023). "One of the high-confidence autism risk genes, SCN2A, is a highly connected hub in this module." (PMID 34433918, 2021). "Pathogenic mutations in SCN2A, which encodes a voltage‐gated sodium channel, are mainly linked to early‐onset epilepsy syndromes but have also been linked to episodic ataxia, intellectual disability, and autism." (PMID 33938619, 2021). "Diseases associated with unusually high rates of autism, such as SCN2A syndromes, provide an opportunity to study specific mutations with high effect sizes in a human genetic context and may reveal biological insights applicable to more common forms of autism." (PMID 32264956, 2020).
autism (continued). "A previous study identified four missense mutation in SCN1A gene, one coding mutation in SCN2A gene from different autism families and suggested that mutations in the sodium channel genes may play a role in autism susceptibility." (PMID 22848613, 2012). "Here, the authors show that Scn2a+/- autism model mice are unable to use past experiences to update visual sensory responses, and that this phenotype derives from a deficit in cortical feedback signals to the superior colliculus." (PMID 41027944, 2025). "Mice heterozygous for both Scn2a and Kcn1, a gene encoding for the pore-forming subunit of the voltage-gated potassium channel KV1.1(Scn2a+/−;Kcna1+/−), have reduced anxiety and autism-like behaviors compared to Scn2a+/− mice." (PMID 39606727, 2024). "MEAs have been deployed to investigate gene mutations associated with monogenic forms of autism in hiPSC-neurons such as CNTN5, EHMT2, KCNQ2, ATRX, and SCN2A." (PMID 37441676, 2023). "In the nonseizure group, the yield was 44% (4/9), including one with SCN2A with autism, one FBN1 with Marfan syndrome, one DMD with muscle dystrophy, and one SPTBN2 with spinocerebellar ataxia." (PMID 33333793, 2020). "As of 2018, 276 patients were identified with SCN2A-mediated disorders, approximately 50% of whom displayed autism." (PMID 32264956, 2020). "Genome-wide scan studies for autism susceptibility genes reported a potential susceptibility region at locus 2q including SCN1A, SCN2A and SCN3A genes." (PMID 30071822, 2018). "Intriguingly, rare mutations within genes encoding similar α subunits, such as SCN1A, SCN2A and SCN3A, have been linked to autism." (PMID 24564958, 2014). "Cells in the later pseudotime stage exhibited specific enrichment in synaptic pathways, characterized by the upregulation of several neuronal markers, including CUX2, glutamate metabotropic receptor genes (GRM1, GRM2, and GRM3), and several autism risk genes, including PTEN, SCN2A, and SHANK2." (PMID 39363111, 2024). "This pattern was consistent with those of other autism risk genes, such as GRIN2B (correlation coefficient (r) = 0.65, p < 2.2e-16), SCN2A (r = 0.64, p < 2.2e-16), and CACNA1D (r = 0.51, p < 2.2e-16), suggesting a coordinated increase during the fetal third trimester." (PMID 39363111, 2024). "Thus, the increased repetitive self‐grooming behavior and abnormal interest in social novelty in Scn2a+/– mice are consistent with autistic‐like features, providing further support for their utility as a mouse model of autism." (PMID 33484493, 2021). "In addition, the ability of partial deletion of Kcna1 to improve ASD phenotypes in Scn2a+/– suggests Kv1.1 subunits as a novel target for therapy in autism due to Scn2a channelopathy." (PMID 33484493, 2021). "Notably, however, Scn2a+/- adult and juvenile mice showed increased direct social interaction, a result often observed in other mouse models of autism that lack, i.e., the excitatory postsynaptic scaffolding protein Shank3." (PMID 31249508, 2019). "For example, in relation to the overall phenotypic landscape of the SCN2A-related disorders, individuals with a novel missense variant are three times more likely not to have autism and almost 20 times more likely to not have any form of intellectual disability." (PMID 33731876, 2021). "Here, we review the findings from experimental models of SCN2A syndromes, including mouse and human cell studies, highlighting the potential role for patient-derived induced pluripotent stem cell technology to identify the molecular and cellular substrates of autism." (PMID 32264956, 2020).
autism (continued). "Emerging evidence suggests that SCN2A may also contribute to schizophrenia and intellectual disability in the absence of autism, although these associations require further investigation." (PMID 32264956, 2020). "The analysis revealed that missense SCN2A variants are largely correlated with terms like “neonatal onset,” “seizures,’ and “no intellectual disability”, while premature termination variants were correlated with terms like “behavioral abnormality,” “autism,” “autistic behavior,” and “ no seizures’’." (PMID 39606727, 2024).